NRAS (NRAS proto-oncogene, GTPase)
Diseases named in the same sentence as NRAS in open-access papers (continued):
Sharing a sentence is not in itself a finding about the gene and the disease.
cancer (continued). "We demonstrate that dual pathway inhibition of the MAPK and PI3K/AKT/mTOR pathway synergistically reduces cell viability in NRAS mutant cancers regardless of their tissue origin." (PMID 25277205, 2014). "In addition to known cancer driver genes such as ERBB2 (6% of cases), NRAS (3%), MET (3%), PIK3CA (1%), AKT2 (1%), TSC1 (1%), and ERBB4 (1%), several putative cancer genes were identified, such as PTPRC, SYNE2, GRIN2A, and CDH10." (PMID 24576404, 2014). "Interestingly, when we investigated a purely NRAS-dependent murine cancer cell line, we observed a much higher baseline level of DUSP4 and DUSP6 compared to its dual NRAS and AKT-addicted counterpart, which is suggestive of a certain exclusivity towards the RAS oncogenic pathway." (PMID 37946160, 2023). "In addition, we subdivided the cancer samples into two groups: (i) tumors that had known clinically relevant mutations in EGFR signaling genes: EGFR, KRAS, NRAS, and BRAF, and (ii) “wild type” tumors that did not have these mutations." (PMID 33748471, 2021). "It was found that BRAF V600E, RET/PTC1 and TERT mutations were associated with aggressive characteristics, whereas BRAF K601E, HRAS, NRAS, KRAS, PAX8-PPARy mutations and tumors with no mutations are significantly less likely to be associated with high risk cancers." (PMID 33910629, 2021). "Compared with HRAS, both KRAS4B and NRAS were enriched for the “Central carbon metabolism in cancer” pathway, which includes proteins from the PIK3/Akt and MAPK pathways, glucose transporters, metabolic enzymes and tyrosine kinase receptors, all being frequently activated in cancer." (PMID 33187149, 2020). "Another group observed that TBK1 is active in mutant NRAS melanoma and promoted migration and invasion of these cells, suggesting that RAS-driven epithelial plasticity may be active in the presence of other RAS isoform-driven cancers." (PMID 31681587, 2019). "Based on these 19 drug-variant combinations, 4 out of 6 sensitive mutations in DEPO (KRAS G12V, BRAF V600E, NRAS Q61K, and KRAS G12D) were significantly associated with sensitivity to at least one of their paired drugs in both the cancer-type-specific and non-specific settings." (PMID 30053901, 2018). "In contrast, reduction of PIP5K1A in the HRAS-mutant and NRAS-mutant human cancer cell lines typically either had no consistent effect or even an increase in the number of viable cells, with the exception of TYKNU cells, in which all three PIP5K1A sgRNAs led to a decrease in cell number." (PMID 30194290, 2018). "The BRAF mutation is known to be mutually exclusive with KRAS and/or NRAS mutations in other cancers; however, in our study, mutations in BRAF did not appear to be exclusive to either the KRAS or NRAS mutation because mutations in KRAS, NRAS, and BRAF were all found in the same patient (patient #1)." (PMID 27634910, 2016). "In addition to the recurrent and early 11p LOH event in fusion negative tumors, mutation of FGFR4, KRAS, NRAS and HRAS frequently occurred at an early time point in the cancers evolutionary history." (PMID 25768946, 2015). "The implementation of the National Genomic Test Directory for Cancer in England and access for all patients to NGS panels may provide greater information on the incidence of non-BRAF-V600E mutations, as well as data for NRAS and KIT." (PMID 40902091, 2025). "However, this may be because HCT116 is a cancer cell line, and NRAS overexpression can no longer augment its migratory capacity." (PMID 32620824, 2020).
cancer (continued). "Genes such as NRAS, SPHK2, FOS, CXCR4, PLD1, GNAI2, and PLA2G4F, and their related biological process terms and pathways, such as apoptosis, MAPK signalling pathway, and cancer signalling pathways, may represent potential targets for OA treatment and diagnosis." (PMID 29968759, 2018). "However, HRAS mutations are rarely seen in human cancers (4%), and whether romidepsin also inhibits transformation caused by the Ras isoforms most commonly mutated in human cancers (KRAS and NRAS; 21 and 8%, respectively) has not yet been addressed." (PMID 19682393, 2009). "Seven other cancer-related genes (BRAF, NRAS, HRAS, ERK1, ERK2, PTEN, and PIK3CA) were found negative for mutations." (PMID 40364006, 2025). "NRAS-mutant cancer tissue samples were not available in TCGA for LAML, ALL, MM, MB, NB, DLBC and SCLC cancer types." (PMID 35534592, 2022). "The enthusiasm for FTIs was tempered when it was discovered that in NRAS and KRAS mutant cancers, the MAPK pathway activation and tumor growth were not significantly suppressed with FTIs." (PMID 34830283, 2021). "Members of the RAS family, such as NRAS, KRAS and HRAS, all of which are of significant importance in cancer biology, are no exception." (PMID 32772213, 2020). "Unfortunately, FTIs failed in clinical trials showing no efficacy against NRAS and KRAS-driven cancers." (PMID 32850962, 2020). "Hierarchical clustering and multi-dimensional scaling found that SB/AKT/c-Met + TAA and SB/AKT/NRas + TAA formed a distinct cluster; the cancer plasmids-TAA combinations were more similar to each other than to their respective cancer plasmids without TAA or TAA alone groups." (PMID 39254423, 2024). "Among cancer plasmids without TAA or TAA alone treatments, pairwise comparison with the negative control found that SB/AKT/NRas + saline had the most differentially expressed genes (550 after multiple comparisons correction), followed by SB + TAA and SB/AKT/c-Met + saline." (PMID 39254423, 2024). "However, some recurrent cancer drivers (KRAS, PI3KCA, NRAS, NF1) were reported to drive non-cancer clonal expansion only in one or two organ systems." (PMID 35078504, 2022).
adenocarcinoma (38 papers, 2009 to 2025). A common cancer characterized by the presence of malignant glandular cells. "Inhibition of the RAS/MAPK pathway can also be a therapeutic modality when the mesonephric-like adenocarcinoma is combined with KRAS/NRAS mutations." (PMID 38444000, 2024). "Recent molecular studies have demonstrated KRAS mutations in most mesonephric adenocarcinomas of the cervix, whereas a smaller number show activating NRAS mutations." (PMID 33570865, 2021). "NRAS was mutated in 6.8% of the adenocarcinoma NOS cohort compared to 0.0% of the mucinous cohort (p = 0.58)." (PMID 32984045, 2020). "Three mutations have been detected in patients with SqCC (10.3% out of SqCC patients; 3/29), and only one mutation in the NRAS gene—in a patient with adenocarcinoma (1.25% out of AC patients; 1/80)." (PMID 28097440, 2017). "NRAS mutation was exclusively found in adenocarcinoma, NOS (3.3%, n = 12/360)." (PMID 37277698, 2023). "They enrolled 153 advanced NSCLC patients with NRAS mutations (predominantly with adenocarcinoma)." (PMID 37509393, 2023). "Demonstration of a KRAS or NRAS mutation may be useful in diagnosing a mesonephric adenocarcinoma and distinguishing this from florid mesonephric hyperplasia, which does not exhibit mutations." (PMID 33570865, 2021). "The first patient was male with left-sided CRC adenocarcinoma and synchronous liver metastases and harbored KRAS c.35G>T (p.Gly12Val) and NRAS c.181C>A (p.Gln61Lys) mutations." (PMID 40075837, 2025). "In contrast, mixed well-to-poorly differentiated adenocarcinomas were less frequent in the BRAF/NRAS group (three of six cases, 50.0%) than in the KRAS (33 of 39 cases, 84.6%) or WT (21 of 27 cases, 77.7%) groups." (PMID 41439081, 2025). "The histological subtype was largely Lieberkuhnian adenocarcinoma (95%), and KRAS, NRAS and BRAF genes were mutated in 58%, 4% and 8% of cases, respectively." (PMID 39796718, 2024). "Their results revealed differences in mutation frequency between adenocarcinoma and SCC, and as was expected, the characteristic activating mutations of adenocarcinoma such as KRAS, HRAS, NRAS, and EGFR were identified only in 3% of SCCs." (PMID 32604993, 2020). "Further studies are warranted to validate these in a larger patient cohort and identify further markers of interest such as ROS1 and RET rearrangements, other EGFR mutants and in NRAS-, KRAS-mutated adenocarcinomas." (PMID 30889898, 2019). "The mutation rate of KRAS was significantly different in different histological types, NRAS and BRAF mutations were only detected in adenocarcinomas." (PMID 30416987, 2018). "Although some nuclei showed PTC-like chromatin clearing, negative staining for TTF1 and GATA3 and the absence of KRAS/NRAS mutations ruled out mesonephric-like adenocarcinoma." (PMID 40959354, 2025). "Stratification of identified mutations by IHC subgroup revealed a striking enrichment of oncogene mutations in adenocarcinoma-like LC tumors (85% of all oncogene mutations, affecting 63% of these cases), including all nine KRAS mutations and the single NRAS (G12D) and MAP2K1/MEK1 (K57N) mutations." (PMID 26124082, 2015). "NRAS and BRAF mutations were only detected in 3.0 and 2.2% of adenocarcinomas, but not detected in other histological types." (PMID 30416987, 2018).
adenocarcinoma (continued). "A study was performed with a customized NGS panel (called SiRe) including six genes [EGFR, KRAS, NRAS (NRAS Proto-Oncogene, GTPase), BRAF, KIT Proto-Oncogene Receptor Tyrosine Kinase (KIT)), Platelet-Derived Growth Factor Receptor Alpha (PDGFRA)] for 194 patients with advanced adenocarcinomas." (PMID 33922637, 2021). "In total, putative actionable genomic targets (FGFR2, BRAF-V600E, MTOR, NRAS, and KDM6A) were identified in 35% of the cases by OncoKB search, an important finding given the high number of fluent transitions from high-grade IEN to adenocarcinoma at the time of diagnosis (14/17 cases)." (PMID 34205964, 2021).
infection (19 papers, 2009 to 2026). The state of being infected such as from the introduction of a foreign agent such as serum, vaccine, antigenic substance or organism. "However, NRAS was the only one of these recurrently mutated genes to remain significantly associated with death from infection after Benjamini and Hochberg false discovery adjustment (FDR, Q > P [P < 0.05]) (odds ratio: 17.51, 95% confidence interval (CI): 2.20–139.40, P = 0.0004); (data not shown)." (PMID 33580200, 2021). "We induced NRAS expression in each cell type using adenoviral Cre, allowed the cells to recover from infection, and then placed the cells in serum-free media for 4 h prior to protein isolation." (PMID 35672316, 2022). "Multivariate analysis in these 400 patients showed that the factors most significantly associated with death from infection were 11q deletion and mutations of the BRAF, NRAS and XPO1 genes." (PMID 33580200, 2021). "In patients with mutation data, the factors significantly associated with death from infection versus all other deaths were 11q deletion (47/162 [29%] versus 40/209 [19%], P = 0.03) and mutations of the BRAF, FBXW7, NRAS and XPO1 genes." (PMID 33580200, 2021). "But we are not aware of any studies, like that cited above for the NRAS gene, which might cast light on the possible mechanisms leading to a susceptibility to fatal infections in patients with a BRAF mutation, nor in those with an FBXW7 or XPO1 mutation." (PMID 33580200, 2021). "Among the panel of 21 genes commonly mutated in CLL, univariate analysis showed that mutations of BRAF, FBXW7, NRAS and XPO1 were significantly associated with death from infection versus deaths not due to infection." (PMID 33580200, 2021). "In the univariate analysis in this subset of 400 patients, 11q deletion was significantly associated with death from infection versus deaths not due to infection, along with mutations of the BRAF, FBXW7, NRAS and XPO1 genes." (PMID 33580200, 2021).
hematologic malignancies (12 papers, 2020 to 2026). "Regarding the specific NRAS p.G13D variant observed in our patient, this mutation has also been described in the past five years across distinct hematologic and non-hematologic disorders." (PMID 41020826, 2025). "For instance, KRAS and NRAS mutations are found in about 5–26% of hematologic diseases, and RAS mutation has been observed in 16% of AML and 5% of MDS patients." (PMID 39770471, 2024). "NGS covering 51 genes related to hematological malignancies revealed NRAS-p.Gly12Asp, PTPN11-p.Asp61Val, PTPN11-p.Thr468Met, KRAS-p.Gly12Val, and CALR-p.Gly108Arg mutations." (PMID 35912172, 2022). "Intriguingly, in comparison to the previous analysis, we observed 6 new non-synonymous SNVs linked to hematological disease, including variations in CBL (1 pt); DNMT3A (3 pts); FLT3 (1 pts), NQO1 (1 pt); NRAS (1 pts) and 2 frameshifts: CEBPA (1 pts) and NBN (1 pts)." (PMID 38612443, 2024). "RAS pathway alterations are associated with hematologic malignancies, however this patient's NRAS p.Gly61Arg mutation is not common in blood cancers." (PMID 33784031, 2021).
hematologic cancers (9 papers, 2015 to 2026). "Hematologic cancers are unusual in that NRAS and KRAS are both mutated at high frequencies, with NRAS mutations predominating." (PMID 37317974, 2023). "T148 phosphorylation preferentially protects KRAS and NRAS from degradation in hematologic cancers." (PMID 41542462, 2026). "Currently, they are no NRAS-mutant-specific drugs to treat hematological cancers because of the numerous challenges associated with this effort, while selective inhibitors of KRASG12V, KRASG12D, and KRASG12C mutants are already being tested in solid tumors." (PMID 39941834, 2025).
colorectal (7 papers, 2013 to 2022).
rectum (4 papers, 2016 to 2023). "NRAS mutation was significantly more frequent in patients > 64 years of age, BRAF mutation in women, and NRAS/BRAF mutations in right colon tumors." (PMID 37886935, 2023).
benign neoplasm (3 papers, 2012 to 2023). A neoplasm which is characterized by the absence of morphologic features associated with malignancy (severe cytologic atypia, tumor cell necrosis, and high mitotic rate). "It is now clear that melanocytic nevi constitute benign neoplasms of cutaneous melanocytes, which frequently harbour oncogenic serine/threonine-protein kinase B-Raf (BRAF) or, less commonly, neuroblastoma ras viral oncogene homolog (NRAS) mutations." (PMID 22549672, 2012).
blood cancer (3 papers, 2019 to 2021). "Similar oncogenic alterations in KRAS, NRAS and HRAS genes are strong causative drivers in a broad variety of solid and hematological tumors with mostly aggressive behavior." (PMID 34771672, 2021).
neurologic disease (2 papers, 2022 to 2024). "Recent studies have identified NRAS, KRAS, MAP2K1, and ARAF mutations in RDD patients without documented neurologic disease." (PMID 35236371, 2022).
inflammation (1 paper, 2021). Aberrant reaction of the microcirculation characterized by movement of fluid and leukocytes from the blood into extravascular tissues. "That inflammation, immune system activation and imbalance, and cell proliferation and adhesion migration were mainly affected by HLA-DRA, SYK, CTLA4, VAV1, NRAS, and JAK3 signaling pathways was suggested to be the potential molecular mechanism for pulmonary inflammation and fibrosis in ACO." (PMID 33869177, 2021).
NRAS also shares sentences with these, for which no sentence is quoted: mucosal (17 papers); superficial spreading melanoma (13); gastrointestinal stromal tumor (3); genetic disorder (3); Hypertension (3); oligodendroglioma (3); retinoblastoma (3); T-Cell Lymphomas (3); Thyroid adenoma (3); uterine cancer (3); adenoid cystic carcinoma (2); autoimmune disease (2); B cell lymphoma (2); cardio-facio-cutaneous syndrome (2); condyloma acuminatum (2); Costello syndrome (2); cyst (2); desmoplastic melanoma (2); embryonal carcinoma (2); essential thrombocythemia (2); Histiocytosis (2); influenza (2); LEOPARD syndrome (2); linear sebaceous nevus syndrome (2); lymphedema (2); mast cell hyperplasia (2); neurofibroma (2); neurofibromatosis (2); neuropathy (2); papillary renal cell carcinoma (2).
A further 143 diseases each share a sentence with NRAS in 2 papers or fewer.